CCR7 (C-C motif chemokine receptor 7)
Diseases named in the same sentence as CCR7 in open-access papers (continued):
Sharing a sentence is not in itself a finding about the gene and the disease.
viral infection (continued). "Recent reports support the hypothesis of unidirectional differentiation of CD56dim from CD56bright, suggesting that the recurrent viral infections might lead to depletion of CD56bright CD16− KIR− NKG2A+CCR7+ NK cells." (PMID 24302998, 2013). "Interestingly, CD8+ T cells genetically modified to constitutively express CCR7 cannot leave the WP and are impaired in their capacity to efficiently clear a viral infection." (PMID 20634957, 2010). "After i.n. infection, there was a markedly reduced proliferative expansion of the CL-4 T cells in the MLN of the CCR7-deficient mice whose lung-residing CD103+ and CD11bhi DC are unable to do emigrate out of the respiratory tract in response to virus infection." (PMID 19145246, 2009). "However, the current study uncovered a previously unappreciated role for CCR7 in iMO recruitment to the blood and brain during encephalitic viral infection and provides a more complete view of how CCR2 and CCR7 have complementary roles in this process under homeostatic conditions." (PMID 38658802, 2024). "Thus, reducing CCR7 during viral infection may inhibit viral invasion, but whether this mechanism is a practical approach to prevent HBV invasion requires further study." (PMID 34218330, 2021). "During viral infection, CD45RA and CCR7 are markers that reflect T-cell antigen experience and homing to lymphoid tissues, respectively, which are important for characterizing T-cell memory subtypes." (PMID 40573882, 2025). "Consistent with CD8+ TM subsets, CD4+ TM cells can be traditionally categorized into CD62L+CCR7+ TCM cells, CD62L-CCR7- TEM cells, and CD69+ TRM cells under bacterial and viral infections." (PMID 40391228, 2025). "Therefore, discrepancies between outcomes in CCR7 expression after viral infections might be also a consequence of distinct cell-to-cell aspects such as the time elapsed after cell infection, the cell development stage at which the infection takes place, or baseline CCR7 expression by host cell." (PMID 34778050, 2021). "Suppression of the CCR7 and CCL19/CCL21 axis results in dysfunction of T-cells during viral infection." (PMID 32731586, 2020). "Overall, results from the different animal models of viral infections suggest CNS infiltrating B cells during viral infection migrate into the CNS in a CXCR3-, CXCR5-, and CCR7-dependent manner whose ligands are also upregulated within the CNS." (PMID 33224101, 2020). "For example, vaccinia virus vaccination was found to elicit long-lived memory cells that expressed intermediate levels of CD27 and lacked CD45RO, and yellow fever vaccination was found to elicit long-lived memory cells that expressed CCR7 and CD45RA." (PMID 37781376, 2023). "Finally, CCR7, MBL2, and MCOLN2 have all been connected to the modulation of host cellular and immune responses in viral infection." (PMID 33705408, 2021). "Increased CCR7 expression on blood CD1c+ MDCs during acute HFRS could indicate that these cells have migrated to the lymph nodes, in response to either direct viral infection, as we could show in vitro, or to pro-inflammatory cytokines in serum of patients." (PMID 28640917, 2017). "In particular, in the course of infection in a self-environment, KIR+ NK cells can acquire CCR7 only when they interact with HLA class I negative CCR7+ cells (e.g., target cells that have undergone tumor transformation or viral infection)." (PMID 27774094, 2016). "These increases were observed both in GFP+ and GFP− cells, indicating that robust viral infection did not irreversibly block CCR7 expression." (PMID 21731495, 2011). "Taken together, these data provide strong evidence that CCR2 and CCR7 play a synergistic role to mediate iMO recruitment during encephalitic virus infection, the latter of which has not been previously reported to be involved in iMO recruitment during viral infection." (PMID 38658802, 2024).
viral infection (continued). "In addition, the absence of CCR7 has been shown to affect the magnitude of protective responses against viral infections in mouse models." (PMID 32471056, 2020). "In the case of human metapneumovirus (HMPV) and human respiratory syncytial virus (HRSV), viral infection of monocyte-derived DCs did not efficiently decrease CCR1, 2, and 5 expression, and did not efficiently increase CCR7 expression." (PMID 23301113, 2013).
lymphoma (32 papers, 2007 to 2025). A malignant (clonal) proliferation of B- lymphocytes or T- lymphocytes which involves the lymph nodes, bone marrow and/or extranodal sites. "We also observed increased expression of CCL5, associated with tumor recurrence, and an increase of CCR7, which controls migration of lymphoma cells into niches." (PMID 36153593, 2022). "CCR7 mediated chemotactic responses to the splenic T-cell zone that led to a significant survival benefit when compared to CCR7-deficient lymphoma cells." (PMID 35203305, 2022). "Cutaneous T-cell lymphoma expresses high levels of CCR7 compared to adult T-cell lymphoma, which are associated with retention of the lymphoma cells in the skin." (PMID 35203305, 2022). "Whole-genome sequencing identified recurrent mutations in several genes including CCR7 in 11% of cases, which was proposed to be a mechanism for homing of the lymphoma cells to secondary lymphoid tissues, where the Epstein–Barr virus can propagate and further expand the lymphoma growth." (PMID 35203305, 2022). "Next-generation sequencing was used to investigate single-nucleotide polymorphisms in adult T-cell leukemia/lymphoma patients from different regions of Japan, where it was found that similar mutation profiles occurred, including in the CCR7 gene, likely responsible for T-cell trafficking." (PMID 35203305, 2022). "For CCR7-dependent B-ALL, CNS entry was linked to ZAP70 activation whereas, for primary central nervous system lymphoma, astrocyte-derived CCL19 retained CCR7-expressing lymphoma cells in the CNS, leading to gliosis and increased risk of gliosis-induced primary central nervous system lymphoma." (PMID 35203305, 2022). "In addition to SNPs, most of the larger CCR7 mutations in adult T-cell leukemia/lymphoma patients were truncations of the C-terminus cytoplasmic domain, which were likely gain-of-function mutations." (PMID 35203305, 2022). "Most of the CCR7 mutations in adult T-cell leukemia/lymphoma patients were truncations of the C-terminus cytoplasmic domain and were associated with elevated membrane localization of the CCR7 receptor, which the authors suggested was likely a gain-of-function mutation." (PMID 35203305, 2022). "Finally, there are many mutations in the C-terminal cytoplasmic domain of CCR7 relevant to adult T-cell leukemia/lymphoma, and mutation at the Trp355* residue was shown to prevent CCR7 internalization, resulting in increased surface receptor expression and a gain of chemotaxis function." (PMID 35281921, 2022). "In conclusion, the data presented here demonstrate that the anti-CCR7 mAb has a notable anti-tumor efficacy, causing a significant delay of the tumor growth rate and metastatic process in the subcutaneous model and also hindering lymphoma cells dissemination in the intravenous model." (PMID 24305507, 2013). "RNA sequencing revealed upregulated expression of chemokine genes, including CCL5, CCL18, and CCL19, in WDL and that of the corresponding chemokine receptor genes CCR4, CCR6, and CCR7 in the lymphoma cells." (PMID 39894788, 2025). "The increased transcript level (TL) of CCR7 in anergic cells was intriguing, as a previous study reported that CCR7 expression in NK cells improves migration toward lymphomas and helps in tumor control." (PMID 38637625, 2024). "Surprisingly, CCR7 expression in mediastinal large B-cell lymphoma cells was low to absent and overall chemokine profile was distinct compared to other lymphomas." (PMID 35203305, 2022). "Our immunohistochemical analysis of the CCL19 and CCL21-ligands of CCR7 demonstrated that the lymphoma cells expressed CCL19, but that CCL21 expression was low in the malignant cells." (PMID 35887224, 2022). "Specific cell invasion of the CNS via CCR7 activation was shown for some leukemias/lymphoma, including human T-ALL, B-ALL and primary central nervous system lymphoma." (PMID 35203305, 2022).
lymphoma (continued). "CCR7 was expressed in 62% of mycosis fungoides patient samples that correlated with the subcutaneous skin expansion of the lymphoma cells." (PMID 35203305, 2022). "The mechanisms of leukemia/lymphoma CNS cell invasion were CCR7 dependent and involved distinct pathways." (PMID 35203305, 2022). "Deleting CCL19 in mice or CCR7 in lymphoma cells was sufficient to prevent central nervous system lymphoma development." (PMID 35203305, 2022). "We also detected high CCR7 expression on the lymphoma cells of the GCB-DLBCL, NGCB-DLBCL, and tFL subgroups." (PMID 35887224, 2022). "A more recent study reported CCR7 expression in 62% (13/21) of specimens as per IHC, and indicated that CCR7 expression strongly correlated with subcutaneous extension of lymphoma cells." (PMID 34778050, 2021). "Most of CCR7’s roles in homeostasis (e.g. cell trafficking, interstitial migration, or survival) are particularly relevant for leukemias and lymphomas, which very often express CCR7 because of their lymphoid origin and/or maturation stage." (PMID 34778050, 2021). "Immunohistochemical staining of MF skin lesions further found that CCR7 expression correlated with subcutaneous extension of lymphoma cells." (PMID 34204115, 2021). "In other related primary lymphomas such as intravascular large B-cell lymphoma and mediastinal large B-cell lymphoma a characteristic decrease in immunodetected CCR7 was described." (PMID 34778050, 2021). "Comparative transcript analysis between MCL and normal B-cells have shown CCR7 mRNA to be significantly up-regulated in lymphoma cells." (PMID 34778050, 2021). "Accordingly, in the syngeneic Eμ-Myc mouse model of BL, CCR7 was found necessary for lymphoma cells to home to LN." (PMID 34778050, 2021). "Growing evidence suggests that cell trafficking orchestrated by the C-C chemokine receptor 7 (CCR7) plays a critical role in the pathophysiology of several leukemias and lymphomas." (PMID 34778050, 2021). "As reviewed above, CCR7 is a single receptor driving immune cells into LN, and for this reason this receptor assumes a central role in the pathogenesis of many leukemia and lymphomas, which very often express CCR7 due to their lymphoid or myeloid origin." (PMID 34778050, 2021). "Consistent with a leading function of CCR7 in lymphoma cell homing, Eμ-Myc cells were preferentially located within proximity to HEVs, at the border of the paracortex and in the cortical ridge." (PMID 34706240, 2021). "Accompanying IHC analyses confirmed that expression of CCR7 was high in infiltrating lymphoma cells." (PMID 34778050, 2021). "For example, bcl2 is an antiapoptotic factor upregulated by the EBV protein LMP1 during latency; ccl3 is a chemokine typically upregulated in lymphomas; and ccr7 is one of the first EBV-induced chemokine receptors documented." (PMID 26121143, 2015). "Enhancer mode activation accounted for the most efficiently selected CIS target genes, including Ccr7 as the most prominent of a set of chemokine receptors driving paracrine growth stimulation and lymphoma dissemination." (PMID 24586197, 2014). "Export of lymphoma cells with Ccr7 insertions is also in accord with the relatively low read/RIS ratio in primary thymic lymphomas." (PMID 24586197, 2014). "It appears that the result of Ccr7/9 activation in Runx2/MYC lymphomas is likely to be paracrine growth stimulation, as expression of the cognate ligands (Ccl19, 21, 25) is restricted to thymic stromal cells." (PMID 24586197, 2014). "The anti-CCR7 mAb treatment (3 × 200 μg) was started on day 2 or 7 to target lymphoma cells in either a peri-implantation or a post-implantation stage, respectively." (PMID 24305507, 2013). "Consistent with a critical role of CCR7-regulated cell migration in lymphoma development, it has been described that CCR7–deficient lymphoma cells have a significant delay in the onset of lymphoma compared to CCR7+ lymphoma cells." (PMID 24305507, 2013).
lymphoma (continued). "Due to their lymphoid origin, many leukemias and lymphomas highly express CCR7 and experience frequent metastasis to the lymph nodes." (PMID 24259307, 2013). "Studies show certain lymphomas express CXCR5 along with CCR7 in malignancies which experience frequent metastasis to the lymph nodes suggesting a role of CXCR5 in lymph node metastasis." (PMID 24259307, 2013). "The chemokine receptor CCR7 mediates lymphoid dissemination of many cancers, including lymphomas and epithelial carcinomas, thus representing an attractive therapeutic target." (PMID 24305507, 2013). "To verify that doxycycline was inhibiting TLX1 expression and activity, we measured TLX1 and CCR7 levels by QPCR in the lymphomas of recipient mice." (PMID 21326611, 2011). "In addition, Ccr7 is required for lymphoma cell lodging to secondary lymphoid organs and ACKR4 expression was inversely correlated with the metastasis capacity of different types of cancer cells." (PMID 39298333, 2024). "As CCL19, the ligand of CCR7, promotes the development of PCNSL through the retention of CCR7 expressing lymphoma cells in the brain, the CCR7-CCL19 axis might also play a role in the evasion of malignant B cells from the brain to the CSF." (PMID 36153593, 2022). "Additionally, it was shown that CCR7 plays a key role in the homing of the tumor cells into the lymphoma-supporting niches in aggressive murine B-cell lymphomas." (PMID 35887224, 2022). "Interestingly, CCR7 was moderately expressed on the majority of the lymphoma cells of GCB- and NGCB-DLBCL and tFL." (PMID 35887224, 2022). "Therefore, we next electroporated NK cells with mRNA coding for the chemokine receptor CCR7, which is known to direct cellular migration to secondary lymphoid tissues, including lymph nodes where hematological malignancies such as lymphoma reside." (PMID 27047492, 2016). "Mice treated with this dosage of anti-CCR7 mAb did not have any evident unwanted effect caused by the treatment (with or without the inoculation of the lymphoma cells) even six months after the administration of the anti-CCR7 mAb (data not shown)." (PMID 24305507, 2013). "CCR7 appears to play an especially important role in leukemias and lymphomas." (PMID 24259307, 2013). "Moreover, this neutralization of the CCR7 axis also induced a strong reduction in viability of lymphoma cells within tumor masses, confirming that in MCL CCR7 overexpression is not only involved in orchestrating migration, but also in directly promotion of survival." (PMID 34778050, 2021). "The B cell homeostatic receptors, CCR7 and CXCR4, contribute to the formation of a supportive niche for lymphoma cells, promoting tumor survival, proliferation, and early relapse." (PMID 40896244, 2025). "The expression of chemokine receptors, CCR4 for CCL5, CCR6 for CCL18, and CCR7 for CCL19, was upregulated in lymph nodes with conspicuous lymphoma infiltration, likely representing their expression in lymphoma cells." (PMID 39894788, 2025). "In POD24‐FLs, weak CXCR3 and CXCR4 expression was found in 13.33% and 40% of lymphoma cells, with moderate CCR3 and CXCR5, and strong CCR7 in 50%, 70%, and 50%, respectively." (PMID 40896244, 2025). "In non‐POD24‐FLs, weak CCR3, CXCR3, and CXCR4 expression was observed in 50%, 11.8%, and 40% of lymphoma cells, respectively, while moderate CXCR5 and strong CCR7 expression was detected in 68.3% and 50%." (PMID 40896244, 2025). "Upregulated expression of CCR4 for CCL5, CCR6 for CCL18, and CCR7 for CCL19 was observed in lymph nodes, where lymphocytes were replaced by lymphoma cells." (PMID 39894788, 2025).
lymphoma (continued). "Deutsch reported that C-C motif chemokine receptors 7 (CCR7), CXCR3, and CXCR7 were more frequently detected in lymphoma cells of HP-positive gastric MALT lymphoma than in inflammatory cells of HP-positive gastritis." (PMID 30999581, 2019). "Compared to lymphoma tissues, tonsils had a significant higher number of TN (CD45RA+CCR7+) or TCM (CD45RA-CCR7+) cells that expressed LAG-3." (PMID 28977875, 2017). "Inhibition of LTβR signaling by anti- LTβR antibody or knockdown of LTα impaired cell interaction between lymphoma cell and stromal cell, potentially by disrupting production of CCL19 and CCL21 by stromal cells which are ligands for CCR7." (PMID 25211095, 2014). "proved that CCR7-modified anti-CD19 CAR-NK cells effectively controlled the growth of CD19-positive lymphoma in mouse models by enhancing the infiltration of CAR-NK cells towards chemokine ligands, CCL9 which produced by lymphoma cells." (PMID 38726000, 2024). "CCR7-expressing CAR NK cells were shown to be more effective than control CAR-NK cells in controlling tumors via the CCL19-CCR7 axis both in vitro and in a murine lymphoma xenograft model." (PMID 39114657, 2024). "Common CCR7 SNPs were found in Japanese adult T-cell leukemia/lymphoma patients, although CCR7 differences were typically epigenetic changes rather than gene mutations in North American patients." (PMID 35203305, 2022). "Combining the CCR7 expression with the CCL19 and CCL21 expression pattern, it seems that CCR7 signaling is altered in the lymphoma setting compared to the non-neoplastic condition." (PMID 35887224, 2022). "CCR7-mediated migratory abilities can be selectively potentiated in leukemia/lymphoma cells (as opposed to their normal counterparts) by pre-exposure or co-incubation with other homeostatic chemokines like CXCL12 or CXCL13, as demonstrated in MCL, BL, or SS." (PMID 34778050, 2021). "The fact that CCR7 is not prominently found in most FL suggests that it has a limited role in the pathophysiology of this lymphoma, which is supported by recent evidence." (PMID 34778050, 2021). "Specific chemokine receptors and adhesion molecules make lymphoma cells capable of “homing in” on certain body sites (e.g., lymph nodes for CCR7 and CXCR4/CXCR5) and this property might be the basis of primary disseminated clinical presentation of lymphoma." (PMID 31947775, 2020). "However, we observed that intratumoral LAG-3+ T cells expressed TEMRA markers (CD45RA+CCR7-), suggesting a terminal differentiation status of LAG-3+ T cells in lymphoma." (PMID 28977875, 2017). "However, and opposed to lymphomas with peripheral involvement, CCR7 was present in the cytoplasm rather than at the cell surface indicating that the receptor may not respond to its corresponding ligands in the same conventional fashion." (PMID 34778050, 2021). "Indeed, it was demonstrated that such delay in lymphoma progression was related to the blockage of migratory signals evoked by CCR7 since the absence of this chemokine receptor did not alter the proliferative and/or apoptotic rates of the CCR7-/- lymphoma cells." (PMID 24305507, 2013).